H19 (H19 imprinted maternally expressed transcript)
Diseases named in the same sentence as H19 in open-access papers (continued):
Sharing a sentence is not in itself a finding about the gene and the disease.
infertile (continued). "Sperm DNA from infertile males can also have methylation defects at H19 at the regulatory region CTCF-binding site 6 (CTCF6) located within the DMR of IGF2-H19." (PMID 38136954, 2023). "Quantitative analysis showed that H19 methylation levels were significantly lower in the group of infertile patients than in fertile controls." (PMID 37108386, 2023). "Overall, the analysis showed that H19 methylation levels were significantly lower in the group of infertile patients than in the fertile controls (SMD −0.87, 95% CI −1.25, −0.49; p < 0.00001)." (PMID 37108386, 2023). "This review highlights the specific effects of lncRNA H19 on both female and male infertility, summarizes the role of H19 in infertility, and provides a theoretical foundation for its potential use as a novel molecular target for infertility treatment." (PMID 37507391, 2023). "Single CpG sites in the CTCF6 binding site of H19 have previously been shown to be differentially methylated in normal and infertile patients." (PMID 32375885, 2020). "Women with DOR had significantly lower serum H19 expression level as compared to women with tubal factor infertility and women with unexplained infertility (p < 0.05)." (PMID 32404103, 2020). "Previous studies reported a higher incidence of epimutations at single CpG sites in the CTCF-binding region 6 of H19 in infertile patients." (PMID 32375885, 2020). "Among the imprinted genes, there were significant differences in the methylation levels of H19 between the infertile males and the fertile controls." (PMID 29136648, 2017). "Interestingly, they found that H19 hypomethylation and SNRPN hypermethylation were strongly correlated with a high risk of infertility, and this risk was potentiated in cigarette smokers." (PMID 38717684, 2025). "Reduced expression of H19 has been shown in the endometrial tissues of infertile women." (PMID 38791310, 2024). "Finally, a statistically significant reduction in H19 methylation levels was also observed in patients with a history of infertility or RPL compared to fertile men." (PMID 37108386, 2023). "In addition, we have found a correlation between MTHFR gene promoter hypermethylation and extensive methylation defects at the paternal imprinted gene H19 in sperm DNAs from infertile males with both normal and abnormal semen parameters." (PMID 34368137, 2021). "In conclusion, our data suggest that aberrant DNA methylation of the H19-DMR and the DAZL gene promoter is associated with single-phenotype defects in sperm production/function in infertile men and further studies are warranted to address the role of epigenetic mechanisms in male infertility." (PMID 24015185, 2013). "Reduced H19 activity increases Let7 activity, which suppresses IGF1R expression at the post-transcriptional level, and lowers ESC proliferation, this may contribute to reduced implantation receptivity, and it is linked to infertility." (PMID 37507391, 2023). "Likewise, the epigenetic alteration in infertile male gametes consists of H19 hypomethylation." (PMID 37108386, 2023). "Also, based on these results, it is not possible to see if decreased methylation at the H19 ICR is caused by ART or infertility." (PMID 29946374, 2018). "Furthermore, H19 expression was declined in the infertile women." (PMID 29137430, 2017). "The paternally imprinted and methylated differentially methylated region (DMR)s of H19 showed hypomethylation, whereas the maternally imprinted and unmethylated DMRs of GNAS and DIRAS3 showed increased methylation in idiopathic infertile males." (PMID 39311136, 2024). "Infertility, bilateral ovarian lesions, recurrence, increased CA125 levels, and revised American Fertility Society stage were all related with expression of H19 in the ectopic endometrium." (PMID 37507391, 2023). "In addition, H19 expression level may be correlated to disease progression and infertility." (PMID 35459174, 2022).
infertile (continued). "In total, we identified the aberrant methylation of H19, GNAS, and DIRAS3 in 19.3%, 21.5%, and 22.2% of the 135 infertile males, respectively." (PMID 30373665, 2018). "The DNA methylation of one paternally (H19) and two maternally (SNRPN and KCNQ1OT1) methylated imprinted genes in sperm samples from 97 infertile males and 31 control subjects was analyzed by bisulfite pyrosequencing." (PMID 29136648, 2017). "Our analyses of LINE1 transposons indicate that abnormal methylation of the H19-DMR and the DAZL gene promoter specifically occurred in OZ and/or AZ sperm of infertile men." (PMID 24015185, 2013). "The results of the present study show that patients experiencing infertility and with oligozoospermia have lower H19 gene methylation levels than those without." (PMID 37108386, 2023). "Aberrant methylation patterns at DMRs of genes such as IGF2, H19, and GTL2 in Y chromosome-containing prospermatagonia during spermatogenesis have been explored as specific epigenetic alterations to maternally imprinted genes of infertile men." (PMID 36061209, 2022). "In addition, abnormal methylation at H19 has been shown at the regulatory region CTCF-binding site 6 (CTCF6), located within the DMR of IGF2-H19, in sperm DNA from infertile males." (PMID 34368137, 2021). "Therefore, in this study, we analyzed the methylation state of the H19-DMR and DAZL promoter in spermatozoa of infertile men with single-factor OZ and single-factor AZ." (PMID 24015185, 2013). "Sperm samples from infertile males with abnormal sperm parameters have been found to have disruptions in the methylation of imprinted genes like MEST and H19, although their prevalence may have been overestimated due to somatic DNA contamination and genetic variation." (PMID 38136954, 2023).
myocardial infarction (31 papers, 2017 to 2025). Gross necrosis of the myocardium, as a result of interruption of the blood supply to the area, as in coronary thrombosis. "Other notable examples include (myocardial infarction-associated transcript) and H19 variants, which are linked to myocardial infarction and increased CAD, respectively." (PMID 38291757, 2024). "Apart from cancer, the top-ranked lncRNA H19 associated with myocardial infarction has been reported to bind directly to miR-103/107 and regulate FADD expression and necrosis." (PMID 28051121, 2017). "Additionally, peripheral blood H19 was presented as a useful diagnostic tool in sepsis, myocardial infarction, osteoarthritis, and epilepsy." (PMID 37189829, 2023). "In addition, H19 is closely related to diseases associated with vessels, such as coronary artery disease, acute myocardial infarction and carotid artery injury." (PMID 30948500, 2019). "It is noteworthy to mention that myocardial infarction led to a significant decrease in H19 levels in rats, which returned to normal after 4 weeks of moderate‐intensity aerobic training." (PMID 39107107, 2024). "Another study found that H19 expression significantly decreased after myocardial infarction in rats but returned to normal levels after a 4‐week endurance training period." (PMID 39107107, 2024). "At the same time, H19 has also been proven to be closely related to pyroptosis by a number of studies, including pneumonia, myocardial infarction and other diseases." (PMID 36127676, 2022). "Recently, aberrant expression of H19 has been detected in acute myocardial infarction (AMI) patients." (PMID 34344446, 2021). "Several lncRNAs, namely, myocardial infarction-associated transcript (MIAT), H19, and metastasis-associated lung adenocarcinoma transcript 1 (MALAT1), have also been reported to be altered in AMI patients, but studies in this regard are still in their infancy." (PMID 34063483, 2021). "As expected, compared with the MI rat that was transfected with Ad‐H19, enforced expression of miR‐22‐3p significantly counteracted the effect of H19 on reducing myocardial infarction size (P < .05)." (PMID 31755219, 2020). "Recent studies reported that a few lncRNAs, including H19, metastasis-associated lung adenocarcinoma transcript 1 (MALAT1), and myocardial infarction-associated transcript (MIAT), were involved in the pathogenesis of DCM in type 1 diabetic animals." (PMID 31653946, 2019). "Enforced expression of H19 attenuates cardiomyocyte apoptosis and reduces inflammation, significantly reduces the size of myocardial infarction, improves long‐term cardiac function and attenuates cardiac fibrosis, whereas knockdown of H19 exacerbates symptoms of myocardial infarction." (PMID 40032652, 2025). "Recent studies have demonstrated that H19 inhibits the development of CVD.H19 interacts with miR-130a-3p and miR-17-5p to modify the radioresistance and chemosensitivity of cardiac carcinoma cells, and protects against acute myocardial infarction by activating autophagy in mice." (PMID 35139769, 2022). "H19 modulates cardiomyocyte apoptosis and acute myocardial infarction by targeting miR-29b." (PMID 34130625, 2021). "Zhang and colleagues found that forced H19 expression could dramatically reduce myocardial infarction size, improve cardiac performance and alleviate cardiac fibrosis by mitigating myocardial apoptosis and decreasing inflammation." (PMID 34344446, 2021). "Enforced expression of H19 could remarkably reduce myocardial infarction size, improve long‐term cardiac function and relieve cardiac fibrosis by mitigating myocardial apoptosis and decreasing inflammation, while H19 knockout exacerbated the symptoms." (PMID 31755219, 2020). "In addition, the lncRNA H19 was significantly downregulated after myocardial infarction." (PMID 40032652, 2025).
myocardial infarction (continued). "Evidence demonstrated that aerobic exercise can decrease cardiomyocytes' apoptosis and heart fibrosis areas following MI via modulating the expressions of myocardial infarction associated transcript (MIAT), H19, and lncRNA GAS5." (PMID 36440025, 2022). "Recently, we found an upregulation of the lncRNA H19 at the infarcted area after myocardial infarction (MI) in a murine model, an experimental model for cardiac remodeling and fibrosis, suggesting lncRNA H19 plays a crucial role during cardiac pathogenesis." (PMID 31588235, 2019). "As a result, H19 regulates cardiac remodeling through different mechanisms, such as transcriptional regulation, and serves as a microRNA sponge to inhibit microRNA function to attenuate myocardial infarction and MI-induced myocardial damage." (PMID 34344446, 2021). "More recently, H19 could inhibit CYP1B1 expression in a PBX3-dependent manner to suppress cell apoptosis and promote cell proliferation, thus attenuating myocardial infarction." (PMID 34344446, 2021). "H19 has been shown to be involved in cardiac pathologies, such as CAD, ischemia/reperfusion (I/R) injury, and myocardial infarction (MI)." (PMID 35946958, 2022).
Hyperglycemia (29 papers, 2016 to 2025). An increased concentration of glucose in the blood. "Meanwhile, melatonin also ameliorated changes in lncRNA H19 and miRNA-29c caused by chronic hyperglycemia." (PMID 35890121, 2022). "We confirmed the existence of alteration in DNA methylation in umbilical cord blood exposed to intrauterine hyperglycemia and reported a functional role in regulating gene associated with insulin-like growth factor 2/H19." (PMID 26840070, 2016). "The H19 gene is also associated with chronic inflammatory diseases 20, and lower expression of H19 may mitigate hyperglycemia-induced inflammation." (PMID 39898248, 2025). "This reduction in angiogenesis could be attributed to hyperglycemia-induced impairment of Akt activation and defects in angiogenesis caused by H19-related impairment of the insulin-PI3K-Akt pathway." (PMID 29334272, 2018). "Our findings suggested that LVSP and ±dp/dt were reduced and LVEDP was elevated in diabetic rats, while enforced expression of H19 could significantly improve left ventricular dysfunction associated with hyperglycemia." (PMID 27903964, 2017). "This study confirms that intrauterine hyperglycemia exposure will result in altered DNA methylation of the imprinted gene IGF2/H19 in cord blood, which in turn affects gene expression." (PMID 39273309, 2024). "The therapeutic potential of H19 has also been tested, leveraging extracellular vesicle-mimetic nanovesicles (EMNVs) to deliver H19 to ECs affected by hyperglycemia." (PMID 39049097, 2024). "The level of methylation of the IGF2/H19 locus in GDM placentas was shown to correlate with the level of intrauterine hyperglycemia, as well as with the birth weight of the neonates." (PMID 39765830, 2024). "In vivo studies have shown that, in healthy mice, H19 absence results in dysregulated glucose metabolism including hyperglycemia, hyperinsulinemia, and intolerant insulin, glucose, and pyruvate tests." (PMID 37065737, 2023). "LncRNA H19 is highly expressed under hyperglycemia and serves as a crucial regulator in many pathophysiological processes of DKD, including the inflammatory response, EMT, cellular proliferation, apoptosis, autophagy, and fibrosis." (PMID 37964955, 2023). "Hyperglycemia-induced reduction of H19 expression was confirmed in the vitreous humor from diabetic patients with proliferative DR as compared with non-diabetic controls." (PMID 35946958, 2022). "H19 knockout inhibited the EndMT process of pulmonary microvascular ECs in a streptozotocin (STZ)-induced hyperglycemia mouse model by H19/TE1 signaling." (PMID 35740920, 2022). "A previous study from our laboratory had demonstrated that in-vivo administration of H19 siRNA induced hyperglycemia, hyperinsulinemia, hyperlipidemia and impaired oral glucose, insulin and pyruvate tolerance in mice." (PMID 35842608, 2022). "For example, lncRNA H19 inhibition in vivo induced hyperglycemia and impaired glucose, insulin, and pyruvate tolerance in liver tissue." (PMID 32765426, 2020). "Our results showed that autophagy was significantly activated in response to hyperglycemia, and enforced expression of H19 in diabetic rats decreased the number of autophagosomes and reduced the expression of LC3-II, BECN1 and ATG7." (PMID 27903964, 2017). "Intrauterine hyperglycemia also decreases the expression of H19 and Igf2 in mouse pancreatic islets of F2 generation offsprings of gestational diabetes mellitus (GDM) mice." (PMID 28814771, 2017). "The relationship between altered methylation level of specific sites of IGF2 and H19 and hyperglycemia should be investigated in depth in animal and cell studies." (PMID 26840070, 2016). "We confirmed the existence of alteration in DNA methylation in umbilical cord blood exposed to intrauterine hyperglycemia and reported a functional role in regulating gene associated with IGF2/H19." (PMID 26840070, 2016).
Hyperglycemia (continued). "This downregulation of H19 in the cord blood and placental tissue in GDM has been associated with alterations in DNA methylation patterns, as demonstrated in GDM, and correlates with the level of hyperglycemia." (PMID 39765830, 2024). "Furthermore, H19 induces hepatic glucose production and gluconeogenesis in the liver, which promotes hyperglycemia and insulin resistance." (PMID 37104004, 2023). "Also, in this study, H19 was identified as an imprinted gene for transducing hyperglycemia from paternal obesity to female offspring." (PMID 37065737, 2023). "Our previous study showed that lncRNA H19 suppression protected the endothelium against hyperglycemia-induced inflammation and oxidative stress by upregulating miR-29b expression and downregulating VEGFA expression, which caused the activation of the AKT/eNOS pathway in endothelial cells." (PMID 35890121, 2022). "Furthermore, they demonstrated that the inhibition of H19 in vivo induced hyperglycemia and hyperinsulinemia and increased the transcription of hepatic gluconeogenic genes." (PMID 34298896, 2021). "Intrauterine hyperglycemia may affect expression of IGF2/H19 through altering methylation level of IGF2/H19." (PMID 26840070, 2016). "Our findings indicated that enforced expression of H19 could remarkably attenuate hyperglycemia-mediated oxidative stress in myocardial tissue." (PMID 27796346, 2016). "LVFS, LVEF, E/A and Ea/Aa ratios, indicators of left ventricular systolic and diastolic function, were found to be reduced in diabetic rats, whereas H19 overexpression could markedly improve hyperglycemia-induced left ventricular dysfunction." (PMID 27796346, 2016). "Conversely, overexpression of H19 leads to a reduction in TGF-β1 levels and can thereby prevent the hyperglycemia-induced EndoMT by blocking the TGF-β-mediated activation of the mitogen-activated protein kinase (MAPK) pathway via extracellular-signal-regulated kinase (ERK) 1/2." (PMID 35946958, 2022).